CD4 (CD4 molecule)
Diseases named in the same sentence as CD4 in open-access papers (continued):
Sharing a sentence is not in itself a finding about the gene and the disease.
helminth infection (continued). "We found that helminth infection modestly increased the frequency of FoxP3+ CD25+ Tregs within the CD4+ T cell compartment in the auricular LN draining the ear skin, and that 2 doses of anti-CD25 significantly reduced the frequency of Tregs in both uninfected and Hb infected mice." (PMID 32508831, 2020). "Skin inflammation in this DBP-FITC CHS model is CD4+ T cell-dependent and we found a significant increase in numbers of these cells in the skin after challenge compared to naïve mice which again, was decreased by prior helminth infection." (PMID 32508831, 2020). "Helminth infections have been reported to affect the immune system by shifting the phenotype of T cells towards the CD4 + T helper type 2 (TH2) cells and T regulatory (Treg) and reduction in TH1 phenotypes thereby, reduction in its associated pro-inflammatory responses." (PMID 33149205, 2020). "ILC2s also regulate and receive feedback from CD4+ T cells during helminth infections." (PMID 31072011, 2019). "Therefore, additional studies are needed to further investigate the role of canine CD4+ CD8+ double-positive T cells in helminth infection." (PMID 28871165, 2017). "Taken together, our data indicate that a high proportion of Mtb-specific CD4 T cells from Tanzanian TB patients have a mixed Th1/Th2 cytokine profile which is observed either in patients with active helminth infection or in a large proportion of patients with positive helminth serology." (PMID 28759590, 2017). "The study hypothesis was that helminth infection might influence the functional profile of Mtb-specific CD4 T cells." (PMID 28759590, 2017). "Asking whether infections with S. ratti led to the expansion of Th2/1 cells as previously shown for other helminth infections, we screened the organs of naïve and infected mice for CD4+ T cells simultaneously expressing GATA-3 and T-bet." (PMID 28676845, 2017). "Activation of naive CD4+ T cells results in the development of several distinct subsets of effector Th cells, including Th2 cells that play a pivotal role in allergic inflammation and helminthic infections." (PMID 28523202, 2017). "Hence, this data supports the observation that helminth-specific CD4+ T cells from co-infected animals are unable to commit to the Th2 lineage but produce the Th1 cytokine IFN-γ in response to a helminth infection instead." (PMID 28791259, 2017). "However, a more recent study has clearly shown that IL-9 is produced early during Nippostrongylus brasiliensis infection of mice by a non-Th2 CD4+ T cell subset and that its production from this subset is sufficient for host protection against worm infection." (PMID 26730582, 2016). "In agreement with this, a negative association of CD4 counts and risk of helminth infection was reported in HIV-infected patients in Uganda." (PMID 25993501, 2015). "In the present study, the role of F4/80+MHC-IIhigh macrophage derived IL-10 might be important for the initial polarization of dermal CD4+ T cells towards their subsequent production of IL-10, as shown in another recent study of helminth infection." (PMID 25974019, 2015). "Also, after antihelminthic therapy, the CD4+ T-cell count significantly increased (P < 0.005) in all treated helminth infections." (PMID 26415705, 2015). "Thus, during chronic helminth infection AAM can arise from recruited Ly6Chigh monocytes via help from CD4+ T cells." (PMID 24967715, 2014). "Our findings suggest that in the presence of coincident helminth infection, the ability to restore homeostatic CD4+ and CD8+ T cell responses in active disease could be worsened." (PMID 25211342, 2014). "Nonetheless, in subjects with helminth infection the median proportion of HLA-DR+/CD38+ CD4 T cells was significantly elevated (2.16% versus 2.63%, p = 0.011) whereas median HLA-DR+/CD38+ CD8 T cell frequencies were moderately increased (5.50% versus 6.86%, p = 0.055)." (PMID 24675895, 2014).
helminth infection (continued). "This review suggests that treatment of helminth infection may result in delayed progression of HIV-1 disease as measured by change in CD4 counts and plasma viral load." (PMID 25419274, 2014). "Moreover, our data also clearly reveal that helminth infections have very little effect on the naive and memory compartmentalization of CD4+ and CD8+ T cells in active TB." (PMID 25211342, 2014). "None of the helminth infections was associated with substantial changes in the expression of CCR5 on memory CD4 T cells." (PMID 24675895, 2014). "As HIV-infection may alter excretion of parasite eggs in stool due to immunodysregulation, we also assessed the impact of immune status (as measured by CD4 count level) on the ability of these assays to detect helminth infection." (PMID 24324729, 2013). "MT is a common cause of systemic immune activation in HIV infection and is associated with reduced frequencies of CD4+ T cells; no data exist, however, on the role of MT in intestinal helminth infections." (PMID 23056659, 2012). "Rises in the number of local CD4+ T cells have been described in several helminth infections." (PMID 21912714, 2011). "In this study we were able to characterise naturally occurring regulatory T cells in a human helminth infection with a more comprehensive marker set, namely CD4+(dim)CD25+(high)FOXP3+CD127low cells and analysed the relationship to activated T cells designated as CD4+CD25+FOXP3−." (PMID 21347311, 2011). "Immunoregulation in response to helminth infection may suppress HIV-1-specific CD4+ and CD8+ proliferation and cytokine production which may compromise control of HIV-1 replication." (PMID 18160978, 2007). "In addition, treatment of helminth infection resulted in a significant increase in absolute CD4 counts (192 versus 279 cells/mm3, p = 0.002)." (PMID 18160978, 2007). "Chronic helminth infection may suppress immune responses directed against HIV-1 and concurrent immune activation may directly lead to more rapid loss of CD4 cells in HIV-1 infected individuals." (PMID 18160978, 2007). "Individuals may acquire helminth infection during the period between the initial measurement of CD4 count or HIV-1 RNA and the de-worming visit and this could result in misclassification of the exposure." (PMID 18160978, 2007). "However, the origin and specificity of the CD4+C25+ population generated by this or other helminth infections have yet to be delineated." (PMID 17563918, 2007). "Altogether, these data along with a recent study that showed IL-4 production during helminth infection transcriptionally alters naïve CD4+ T cells, demonstrate that even after removal, cytokine may have long-term impacts on the naïve CD4+ T cell state or responsiveness to stimuli." (PMID 39866877, 2025). "More studies showed that helminth infection rapidly expanded natural CD4+Foxp3+ regulatory T cells (tTregs) to inhibit host protective immunity against helminth infection while adaptive pTregs were differentiated slowly with limited protection against helminth infection." (PMID 34336843, 2021). "Thus, ILC2s and CD4+ T cells are interdependent in responding to helminth infections." (PMID 31072011, 2019). "However, with the further understandings and definitions of CD4+T cells, new T-helper cell subsets such as Th17 cells and regulatory T cells were also found as it proved that these cell subsets play crucial roles in helminth infection." (PMID 28151995, 2017). "CD4 counts were not correlated with the risk of harboring helminth infections." (PMID 25993501, 2015). "Furthermore, published data supports the hypothesis that helminth infections can influence important parameters of HIV infection such as CD4+ lymphocyte counts and HIV viral loads." (PMID 23849678, 2013). "However, the observed loss in CD4+ cells in patients with helminthic infections does not reach the level seen in HIV infection." (PMID 22860137, 2012).
helminth infection (continued). "In contrast, CD4 decline appears more related to immune activation status and changes in regulatory T cell expression and function which may resolve more slowly following treatment of helminth infection." (PMID 18160978, 2007). "Another study showed that elevated IL-4 presence during helminth infections results in the expansion of an IL4-induced naïve CD4+ T cell cluster, and these naïve CD4+ T cells are biased towards a hyporesponsive state upon alum treatment." (PMID 39866877, 2025). "Targeted deletion of BCL6 within this subset reduces the frequency of CX3CR1+CD4+ T cells during infection, underscoring the role of BCL6 in sustaining Th2 responses to helminth infections." (PMID 40634636, 2025). "While CD4+ Tregs are known to modulate type 2 immunity, CD8+ Treg are less well studied in helminth infections." (PMID 39140728, 2024). "LTBI positive individuals (QFT+) with helminth infection showed a lower frequency of IFN-γ+CD4+ T cells in PPD (p< 0.05) and SEB (p< 0.05) stimulation, as well as IFN-γ+CD4- T cells with a similar pattern, when compared to helminth negative LTBI subjects." (PMID 36662839, 2023). "Meanwhile, CD4+CD25+FoxP3+ Tregs play an important role in parasite-mediated down-regulation of the immune system, and most helminth infections result in recruitment of Tregs." (PMID 29843794, 2018). "Other studies also showed that Th2 subset of CD4+ T-cells dominate a chronic helminths infection and facilitate HIV disease progression with Th1 suppression in helminth infections." (PMID 26415705, 2015). "Our data reveal significant alterations in the baseline frequencies of mono - and multifunctional CD4+ and CD8+ Th1 and Th17 cells in TB-infected individuals with active helminth infection." (PMID 25211342, 2014). "Human and animal studies have shown that individuals with TB and helminthiasis have a reduction in IFN-γ secretion and the number of T CD4 lymphocytes compared to subjects with TB alone." (PMID 24879374, 2014). "Eradication of helminth infections in HIV-positive patients significantly inhibits the progression of HIV infection by attenuation of the plasma viral load and increasing CD4 counts." (PMID 24575099, 2014). "Together these results indicate that, during chronic helminth infection, CD200R and its ligand CD200 are upregulated and co-expressed in chronically activated CD4 T cells." (PMID 22496920, 2012). "Changes in CD4 and CD8 T cell counts, together with increased activation of these T cell subpopulations, have already been reported for helminth infections." (PMID 21909439, 2011). "On the other hand, CD4+CD25+Foxp3+ Treg cells have been shown to play key roles in animals and humans with helminth infections." (PMID 21912714, 2011). "Of note, while germ free mice were also reported in another study to not have altered naïve CD4+ T cell subsets, helminth infection led to the emergence of a new IL-4 induced cluster in the naïve CD4+ T cell compartment." (PMID 39866877, 2025). "Helminth infection did not alter the production of IL-17, IFNγ, or IL-10 by antigen-specific CD4+ T cells in the draining lymph nodes, as determined by re-stimulation of a defined number of cells with recombinant H1." (PMID 36753434, 2023). "Furthermore, there was a significant (p < 0.01) increase in Rora-expressing CD4 T cells expressing a tissue-resident marker, CD103 (CD4+CD103+Rora-YFP+), after helminth infection." (PMID 37387671, 2023). "Overall, these data demonstrated a significant impairment of the type-2 response in the absence of IL-17A during helminth infection, with lung CD4+ T cells failing to become fully activated and produce type-2 cytokines." (PMID 32636457, 2020). "In one study on recent immigrants to the UK, those patients with helminth infection showed a significant increase in CD4+ FOXP3+ regulatory T cells compared to those without helminth infection." (PMID 31294001, 2019).
helminth infection (continued). "Multivariable analyses further confirmed a link between W. bancrofti infection and systemic activation of CD4 T cells independent of age, fever, gender or other helminth infections." (PMID 31425508, 2019). "CD4+ and CD8+ T cells are central players in immunity to helminth infections." (PMID 29795573, 2018). "DNA vaccines have been shown to be capable of eliciting balanced CD4+ and CD8+ T cell responses as well as humoral immune responses in small-animal models, which will be advantage to induce protective immune response against helminth infection." (PMID 28069101, 2017). "Few studies have investigated the effect of helminth infections on CD4 cell count in HIV negative, and little is known about possible systemic effects of schistosomiasis on the immune system." (PMID 25768005, 2015). "CD4+ T cell help is required for AAM during chronic helminth infection, but not in acute wound healing models of alternative activation." (PMID 24967715, 2014). "The CD4+ cell levels in this subgroup were similar to the subgroup without evidence of helminth infection (egg-IgElo) and in both cases were above 0.2 cells/ml and lower than the other two subgroups." (PMID 25209883, 2014). "We compared the frequencies of HLA-DR+ and HLA-DR+/CD38+ on CD4 and CD8 T cells and in addition studied the CCR5 expression density on CD4 T cells at 1–3 months in subjects with and without helminth infection at baseline." (PMID 24675895, 2014). "The expansion of CD4+Foxp3− Teff cells was also reduced in the absence of ICOS as observed in other helminth infections 28–31." (PMID 23319295, 2013). "The resulting measurement bias would be expected to result in lower CD4 counts in those with helminth infection, not higher counts as observed." (PMID 20361031, 2010). "Changes in CD4 counts were compared between individuals treated for helminth infection and individuals who were not infected with helminths at baseline in 3 studies." (PMID 18160978, 2007). "Since helminthes infections promote a Th2 immune response, individuals with helminthes might be expected to have lower CD4 + T cell counts than those without." (PMID 32033581, 2020). "We show here that patients with concurrent natural helminth infections and MS condition (HIMS) had an increased expression of the negative regulatory TAM receptors in antigen-presenting cells and their agonist GAS6 in circulating CD11bhigh and CD4+ T cells compared to patients with only MS." (PMID 33347509, 2020). "We found significantly higher frequencies of HLA-DRpos and HLA-DRpos/CD38pos as well as ‘‘effector-like” memory (CD27negCD45ROpos) CD4 T cells in participants infected with W. bancrofti compared to individuals with other helminth infections or without helminth infection." (PMID 31425508, 2019). "The role of CD4+ and CD8+ T cell subset distribution and the association between memory T cell subsets and the common γc cytokines (IL-2, IL-4, IL-7, IL-9 and IL-15) in helminth infections has not been explored well." (PMID 29795573, 2018). "However our data clearly shows that independent of helminth infection, activated HLA-DR+ CD4 T cells express very high levels of CCR5 on their surface potentially facilitating cell entry of HIV." (PMID 24675895, 2014). "Indeed, we have previously shown that CD4+ T cells are required for maintaining AAM during chronic helminth infection, but not in acute models of wound healing." (PMID 24967715, 2014). "However, most cross-sectional and other observational studies have failed to provide evidence that decreased CD4+ T cells and increased HIV-1 viral loads is associated with heavy helminth infections." (PMID 23849678, 2013). "We accordingly tested whether B cells with regulatory capacity are generated by a chronic helminth infection, extending our earlier findings in the C57BL/6 strain, that both CD4+CD25+ and CD4− subsets from H. polygyrus-infected mice are able to down-modulate allergic inflammation." (PMID 20306466, 2010).
helminth infection (continued). "Thus, the differential effect of helminth infection on the CTB and LPS immune responses may implicate CD4+ T cells as a target of helminthic immunomodulation." (PMID 19333369, 2009). "In this systematic review we evaluated the evidence to date that treating helminth infection in HIV-1 and helminth co-infected individuals may impact HIV-1 progression by decreasing HIV-1 virus (HIV-1 RNA), attenuating CD4 decline, or delaying the onset of symptoms of AIDS." (PMID 18160978, 2007). "The cytokine profile also confirmed that rTsPmy-pulsed DCs stimulated T. spiralis-infected mouse CD4+ cells to secrete IL-4, IL-10, TGF-β and IL-17A, but not IFN-γ, consistent with the Th2-skewed immune response induced by helminth infections." (PMID 27809931, 2016). "The impairment in CD4+ and CD8+ T cell cytokine responses was antigen-specific as polyclonal activated T cell frequencies were equivalent irrespective of helminth infection status." (PMID 25211342, 2014). "Independent of helminth infection status, CD38 expression alone was a characteristic of “naïve” CD27−/CD45RO− CD4 and CD8 T cells, whereas co-expression with HLA-DR was exclusively detected on memory T cells." (PMID 24675895, 2014). "The CD4+ and CD4:CD8 ratio was similar to the values for the egg-IgElo subgroup (without evidence of helminth infection)." (PMID 21999928, 2011). "Finally, although CD4+ TRM cells can produce IFNγ/IL-17, and IL-4/IL-13 following helminth infection, their production of IL-10 has not previously been reported." (PMID 25974019, 2015). "Interestingly the Th1 response to T. gondii was not diminished in CD4+ and CD8+ T cells in co-infected animals, since both subsets were able to produce similar amounts of IFN-γ in contrast to other studies, where the helminth infection precedes the protozoan infection." (PMID 28791259, 2017).